HPS5 (HPS5 biogenesis of lysosomal organelles complex 2 subunit 2)
Description:
May regulate the synthesis and function of lysosomes and of highly specialized organelles, such as melanosomes and platelet dense granules. Regulates intracellular vesicular trafficking in fibroblasts. May be involved in the regulation of general functions of integrins.
Synonyms: Ru2; AIBP63; BLOC2S2
Tractability: PROTAC: ubiquitination databases record sites on it; its protein half-life has been measured.
Gene: Protein-coding gene on chromosome 11 (18,278,668 to 18,322,523, reverse strand). Ensembl gene ENSG00000110756.
Subcellular location: Cytoplasm, cytosol
Subcellular location (Human Protein Atlas): Cytosol
Gene Ontology:
Molecular function: protein binding
Biological process: developmental pigmentation; melanosome assembly; platelet dense granule organization
Cellular component: BLOC-2 complex; cytosol; cytoplasm; early endosome
Genetic constraint (gnomAD): Loss-of-function variants: 69 observed, 105.74 expected, observed/expected ratio (o/e) 0.65, 90% interval 0.54 to 0.8. The upper end of that interval is the gene's LOEUF score, 0.8, which puts it in group 3 of 6, group 1 being the genes least tolerant of losing a copy. Missense variants: 1,112 observed, 1,225.5 expected, observed/expected ratio (o/e) 0.91, 90% interval 0.86 to 0.95. Synonymous variants: 431 observed, 445.86 expected, observed/expected ratio (o/e) 0.97, 90% interval 0.89 to 1.05.
Gene-disease validity (ClinGen):
ClinGen rates the evidence that HPS5 causes each of these diseases.
Hermansky-Pudlak syndrome 5 (autosomal recessive): Definitive.
Homologues: Orthologues: chimpanzee HPS5 (99% identical), macaque HPS5 (96% identical), rabbit HPS5 (88% identical), dog HPS5 (88% identical), guinea pig HPS5 (86% identical), mouse Hps5 (81% identical), rat Hps5 (80% identical), tropical clawed frog hps5 (60% identical), zebrafish hps5 (50% identical), Drosophila melanogaster p (19% identical). Paralogues in human: TECPR2 (19% identical).
Diseases named in the same sentence as HPS5 in open-access papers:
HPS5 is named in the same sentence as 23 diseases in open-access papers, as found by Europe PMC text mining. Sharing a sentence is not in itself a finding about the gene and the disease. The quoted sentences say what the papers report.
Hermansky-Pudlak syndrome (7 papers, 2017 to 2025). Hermansky-Pudlak syndrome (HSP) is a multi-system disorder characterized by oculocutaneous albinism, bleeding diathesis and, in some cases, neutropenia, pulmonary fibrosis, or granulomatous colitis. "Additional pigmentation-related genes, such as ASIP (Agouti-signaling protein) and HPS5 (Hermansky-pudlak syndrome 5), also exhibited missense variants." (PMID 40610894, 2025). "Hypopigmentation characterized also snow white zebrafish mutant carrying a hps5 gene mutation, reproducing Hermansky-Pudlak syndrome (HPS) in fish models." (PMID 35713744, 2022). "With a higher MAF (0.228), we detected an SNP in HPS5 (Hermansky-Pudlak syndrome)." (PMID 33562295, 2021). "Some other monogenetic lung disorder-related genes were enriched in specific SAE cell types, including BC (LTBP4, ELN, cutis laxa), ionoctyes (HPS5, Hermansky-Pudlak syndrome), mucin-producing cells (COL1A1, Ehlers-Danlos syndrome), and neuroendocrine cells (BMPR2, pulmonary hypertension)." (PMID 32727470, 2020).
oculocutaneous albinism (4 papers, 2013 to 2025). Oculocutaneous albinism (OCA) describes a group of inherited disorders of melanin biosynthesis characterized by a generalized reduction in pigmentation of hair, skin and eyes and variable ocular findings including nystagmus, reduced visual acuity and photophobia. "Lastly, we showed injection of Cas9 mRNA and Hps5 guide RNAs resulted in induced mutations in Hps5 and embryos displaying oculocutaneous albinism phenotypes similar to casper mutants, demonstrating Hps5 disruption underlies the casper phenotype." (PMID 28739598, 2017). "In humans, mutations in the BLOC-2 complex member Hps5 result in Hermansky-Pudlak Syndrome type 5, which is characterized by oculocutaneous albinism, and bleeding diathesis." (PMID 28739598, 2017). "The HPS5 gene has been associated with Hermansky–Pudlak syndrome (HPS), characterized by oculocutaneous albinisms (with variable manifestations), bleeding diathesis, and, in some individuals, pulmonary fibrosis, granulomatous colitis, and/or immunodeficiency." (PMID 40426944, 2025). "In zebrafish, the snow white mutant phenotype, oculocutaneous albinism, was shown to result from an I76N point mutation in the WD40 domain of Hps5." (PMID 28739598, 2017).
atherosclerosis (1 paper, 2022). A disease characterized by the build-up of fatty material and calcium deposition in the arterial wall resulting in partial or complete occlusion of the arterial lumen. "The HPS5 gene from which hsa_circ_0000280 originates has not been investigated from the viewpoint of atherosclerosis." (PMID 36477660, 2022).
kidney failure (1 paper, 2025). An acute or chronic condition that is characterized by the inability of the kidneys to adequately filter the blood. "While we have identified promising potential modifier variants in NFU1, DMD, HPS5, CLDN8 and CLDN17, their functional impact on FHHNC progression towards kidney failure remains to be characterized." (PMID 40173198, 2025).
infection (4 papers, 2016 to 2025). The state of being infected such as from the introduction of a foreign agent such as serum, vaccine, antigenic substance or organism. "Our study found that HPS5-SQ infection can cause reduced levels of TJs, impair TJs integrity in piglets’ lungs, and break through the epithelial barrier of piglets’ lungs." (PMID 36228044, 2022). "To determine that HPS5-SQ breached the porcine epithelial barrier and caused porcine lung injury via a paracellular pathway, we firstly assayed piglets’ lung damage and TJs expression by H&E stain and western blot in the infection of HPS5-SQ." (PMID 36228044, 2022). "During early HPS5-SQ infection, autophagy cutting off cell membrane Claudin-1 replenishment disrupted STEC cytoplasmic Claudin-1 and breached the porcine airway epithelial barrier by injuring paracellular." (PMID 36228044, 2022). "In the infection of HPS5-SQ or pretreated with CCCP for 6 and 12 h, Claudin-1 and Parkin level in STEC was downregulated, and EGFP-Claudin-1 expression was quickly diminished." (PMID 36228044, 2022). "At the same time, the expression of p62 decreased from 9–12 h, and Baf-A1 inhibited the decrease of LC3BII in the infection of HPS5-SQ in 12 h." (PMID 36228044, 2022). "Here we show that STEC Claudin-1 covering mitochondria is enveloped and degraded by autophagy in the infection of HPS5-SQ." (PMID 36228044, 2022). "Indirect immunofluorescence staining (IFA) and Western blot were used to detect Claudin-1 in cells to explore the effect of HPS5-SQ infection on STEC Claudin-1." (PMID 36228044, 2022). "HPS5-SQ infection resulted in disordered porcine respiratory epithelial cells, suggesting disruption to the porcine respiratory epithelial barrier, according to H&E staining of swine lung tissue sections." (PMID 36228044, 2022). "We observed that Hps5 infection with a bacterial:cell multiplicity of infection (MOI) of 1:10 induced the most significant LC3- II level at 6 h (p < 0.001)." (PMID 27703447, 2016). "Western blotting, laser confocal microscopy, and electron microscopy showed that Hps5 infection induced obvious autophagy in PK-15 cells." (PMID 27703447, 2016). "In the infection of HPS5-SQ, fragmented mitochondria were encapsulated by LC3." (PMID 36228044, 2022). "At the same time, STEC Claudin-1 decreased in the infection of HPS5-SQ for 12 h." (PMID 36228044, 2022). "In summary, these results demonstrate that Hps5 infection induces autophagy in PK-15 cells." (PMID 27703447, 2016). "Compared with live Hps5 infection, UV-inactivation Hps5 induced weak autophagy." (PMID 27703447, 2016). "We examined the immunoprotective role of HPS_06257 against HPS5 (an HPS_06257-expressing strain) and HPS11 (an HPS_06257-null strain) infections." (PMID 35878359, 2022). "Therefore, HPS5-SQ infection is more likely to activate mitophagy, not autophagy, to degrade mitochondria." (PMID 36228044, 2022).
HPS5 also shares sentences with these, for which no sentence is quoted: albinism (3 papers); arthrogryposis (1); Chediak-Higashi syndrome (1); cholestasis (1); congenital disorder of glycosylation (1); cutis laxa (1); Ehlers-Danlos syndrome (1); granulomatous colitis (1); Griscelli syndrome (1); Immunodeficiency (1); lung disorder (1); Menkes syndrome (1); metabolic disorder (1); oculocutaneous albinism type 1 (1); pulmonary fibrosis (1); pulmonary hypertension (1); renal dysfunction (1); X-linked ocular albinism (1).